HCRTR1 (hypocretin receptor 1)
Description:
G protein-coupled receptor that binds the neuropeptide orexin-A with high affinity, and orexin-B with lower affinity, two peptides derived from a common precursor, prepro-orexin. Its activity is mediated via a G(q)- protein-coupled pathway, which activates the phosphatidylinositol-calcium second messenger system in response to orexin-A binding. In addition to G(q)-mediated signaling, orexin-A stimulation also promotes beta-arrestin recruitment, leading to receptor internalization. Plays a significant role in the regulation of food intake (By similarity).
Synonyms: Ox1R; ORXR1; OXR1
Tractability: Small molecule: an approved drug acts on it; a structure with a bound ligand is known; a high-quality ligand is known; it belongs to a druggable protein family. Antibody: UniProt places it where antibodies can reach, with high confidence; its Gene Ontology location is reachable by antibodies, with high confidence; UniProt predicts a signal peptide or a membrane-spanning region. PROTAC: a small molecule that binds it is known. Other modalities: a drug acting on it is in phase 2 or 3 trials.
Target class: Short peptide receptor (family A GPCR); Family A G protein-coupled receptor; Peptide receptor (family A GPCR); Orexin receptor; Membrane receptor
Chemical probes: BI-5121 (high quality)
Gene: Protein-coding gene on chromosome 1 (31,617,660 to 31,632,518, forward strand). Ensembl gene ENSG00000121764.
Subcellular location: Cell membrane
Pathways (Reactome):
Signal Transduction: G alpha (q) signalling events; Orexin and neuropeptides FF and QRFP bind to their respective receptors
Gene Ontology:
Molecular function: orexin receptor activity; protein binding; G protein-coupled receptor activity; peptide hormone binding
Biological process: neuropeptide signaling pathway; phospholipase C-activating G protein-coupled receptor signaling pathway; regulation of cytosolic calcium ion concentration; cellular response to hormone stimulus; chemical synaptic transmission; feeding behavior; G protein-coupled receptor signaling pathway
Cellular component: plasma membrane; membrane; synapse
Genetic constraint (gnomAD): Loss-of-function variants: 28 observed, 41.75 expected, observed/expected ratio (o/e) 0.67, 90% interval 0.5 to 0.92. The upper end of that interval is the gene's LOEUF score, 0.92, which puts it in group 3 of 6, group 1 being the genes least tolerant of losing a copy. Missense variants: 482 observed, 586.24 expected, observed/expected ratio (o/e) 0.82, 90% interval 0.76 to 0.89. Synonymous variants: 209 observed, 240 expected, observed/expected ratio (o/e) 0.87, 90% interval 0.78 to 0.98.
Homologues: Orthologues: chimpanzee HCRTR1 (99% identical), macaque HCRTR1 (98% identical), pig HCRTR1 (96% identical), dog HCRTR1 (94% identical), rabbit HCRTR1 (94% identical), guinea pig HCRTR1 (92% identical), mouse Hcrtr1 (92% identical), rat Hcrtr1 (92% identical). Paralogues in human: HCRTR2 (67% identical), NPFFR1 (31% identical), NPFFR2 (28% identical), GALR1 (24% identical), CCKAR (23% identical), CCKBR (22% identical), QRFPR (21% identical), AVPR2 (19% identical), GALR3 (19% identical), OXTR (18% identical), AVPR1A (17% identical), FFAR4 (17% identical), and 4 more.